CXCL13 (C-X-C motif chemokine ligand 13)
Diseases named in the same sentence as CXCL13 in open-access papers (continued):
Sharing a sentence is not in itself a finding about the gene and the disease.
asthma (6 papers, 2015 to 2025). "In summary, measurement of CXCL13 levels in plasma may provide diagnostic parameters for assessing airway inflammation and monitoring asthma exacerbation." (PMID 35165593, 2022). "Then, the genes selected by the two methods were crossed, and finally, the key genes involved in the progression of asthma to UC (CXCL13, NOS2, TCN1, CHI3L1 and TIMP1) were obtained." (PMID 40443529, 2025). "It has been reported that CXCL13 levels in bronchoalveolar lavage fluid (BALF) fluid were elevated significantly in asthma patients relative to normal controls." (PMID 35165593, 2022). "Total immunoglobulin E (IgE) and CXCL13 protein levels were measured in the plasma of patients with asthma exacerbations and healthy controls by specific enzyme-linked immunosorbent assay (ELISA)." (PMID 35165593, 2022). "CXCL13 protein levels were increased significantly in the asthma group relative to healthy controls." (PMID 35165593, 2022). "CXCL13 chemokine levels were increased significantly in the asthma group (mean 50 pg/ml) in comparison to normal controls (3.6 pg/ml, P < 0.0001)." (PMID 35165593, 2022). "Up to date, the role of CXCL13 has not been investigated in well phenotyped asthmatic patients, and our study provides the first information on CXCL13 expression differences in a natural model of asthma." (PMID 26292153, 2015). "As a chemokine essential for germinal center formation and B cell polarization, CXCL-13 may also contribute to local IgE production in asthma." (PMID 40529570, 2025). "Increased expression of CXCL13 was positively associated with sputum eosinophils and eosinophil cationic protein (ECP), demonstrating that CXCL13 plays an important role in the pathophysiology of childhood asthma and the possibility for use as additional parameters in asthma diagnosis." (PMID 35165593, 2022). "Consistently, it has been found that B-cell follicles were observed in bronchial lung tissue sections from patients with asthma and increased significantly at the severity of asthma relative to healthy controls, and increased B cells were positively correlated with increased expression of CXCL13." (PMID 35165593, 2022). "Collectively, this suggests that CXCL13 may be used as a potential maker to evaluate acute exacerbation of asthma." (PMID 35165593, 2022). "The current study is designed to examine the airway inflammation in bronchial asthma by measuring the plasma levels of CXCL13 protein in patients with asthma exacerbation and to evaluate the expression of the CXCR5 receptor as a potential parameter to assess airway inflammation." (PMID 35165593, 2022). "Collectively, targeting CXCL13 or blocking CXCR5 may contribute to asthma treatment and reduce the severity of asthma." (PMID 35165593, 2022). "This study is aimed to evaluate plasma levels of CXCL13 and its receptor CXCR5 in Saudi patients with asthma exacerbation relative to healthy controls." (PMID 35165593, 2022). "This study was carried out to assess the plasma levels of CXCL13 chemokine and its receptor CXCR5 as potential biomarkers in asthma exacerbation." (PMID 35165593, 2022). "Also, CXCL13, which was significantly upregulated in RAO samples upon stimulation with LPS/HDE, has been recently proposed as a target gene in asthma treatment based on experiments performed in a mouse asthma model." (PMID 26292153, 2015).
chronic obstructive pulmonary disease (6 papers, 2015 to 2021). A chronic and progressive lung disorder characterized by the loss of elasticity of the bronchial tree and the air sacs, destruction of the air sacs wall, thickening of the bronchial wall, and mucous accumulation in the bronchial tree. "In Vuga’s study, the CXCL13 levels were several times higher in IPF patients compared with chronic obstructive pulmonary disease (COPD) and a healthy group." (PMID 35011819, 2021). "Lung B cells are a major source of CXCL13 and it has a positive role in the lymphoid neogenesis in chronic obstructive pulmonary disease through a LT receptor and toll-like receptor signaling." (PMID 30345018, 2018). "In chronic obstructive pulmonary disease (COPD), TLS B cells have been shown to secrete both CXCL13 and LT." (PMID 25755654, 2015). "CXCL13 and CCL19 have been shown to be controlled by LT-dependent mechanisms in a smoke-exposed chronic obstructive pulmonary disease (COPD) model." (PMID 30972065, 2019).
Cognitive impairment (6 papers, 2020 to 2025). Abnormal cognition is characterized by deficits in thinking, reasoning, or remembering. "Cxcl13, Ccl2 and Ccl19 are 3 pro-inflammatory chemokines previously associated with cognitive impairments and that are also upregulated in AD, Ccl19 being a peripheral biomarker." (PMID 41216177, 2025). "Recombinant CXCL13 induced cognitive deficits and increased the expression of phospho-ERK as well as IL-1β and TNF-α in hippocampus of wild-type mice, but not CXCR5−/− mice." (PMID 33161894, 2020). "Inhibition of either CXCL13 or CXCR5 effectively rescues post-operative cognitive deficits." (PMID 40914484, 2025). "Our data clearly demonstrate that surgical intervention induced CXCL13 release and an increase in CXCR5 expression followed by cognitive impairment as observed in behavioral tests, and that inhibition of CXCL13/CXCR5 signaling attenuated surgery-induced cognitive impairment." (PMID 33161894, 2020). "In the present study, CXCL13 mRNA in the hippocampus was upregulated 1 day after surgery and remained elevated for more than 7 days in surgically treated mice with cognitive impairment; Western blotting and immunostaining further showed upregulated CXCL13 protein in the hippocampus." (PMID 33161894, 2020). "Knockout of CXCL13 or CXCR5 suppresses ERK phosphorylation and mitigates surgery-induced cognitive impairment." (PMID 40914484, 2025). "Expression of CXCL13 and CXCR5 is altered in intractable temporal lobe epilepsy patients and epileptic rats that show neurodegeneration and cognitive impairment." (PMID 33161894, 2020). "In light of the pivotal role of immune parameters (e.g., CXCL13, IL21, IL6, and CCL20) in the distinct microbial composition at early liver disease stages and in general with cognitive impairment, we determined which specific bacterial taxa are related to these patterns." (PMID 41035890, 2025).
leukemia (6 papers, 2008 to 2023). A malignant (clonal) hematologic disorder, involving hematopoietic stem cells and characterized by the presence of primitive or atypical myeloid or lymphoid cells in the bone marrow and the blood. "Then, it is proved that adipocytes attract T‐ALL cells by releasing CXCL13 and support leukemia cell survival by activating the Notch1 signaling pathway via DLL1 and Notch1 binding." (PMID 37072664, 2023). "Gene expression profile analysis revealed a significant increase in Cxcl13 mRNA levels in stromal cells (mSSC) cultured with leukemia as compared to control cells." (PMID 29725010, 2018). "Together, these findings indicate that leukemia promotes a retinoic acid-enriched microenvironment that contributes, at least in part, to CXCL13 induction." (PMID 29725010, 2018). "Having established that leukemia promotes increased retinoid metabolism, and that RA controls CXCL13 in stromal cells, we then assessed the distribution of CXCL13 during leukemia development." (PMID 29725010, 2018). "Although we found that CXCL13 was also expressed by FDCs, our results indicate that to a major extent follicular stromal cells different from FDCs express CXCL13 during leukemia progression." (PMID 29725010, 2018). "Such a phenomenon has been reported for leukaemias, where CXCL13-expressing malignant B cells showed an increased resistance against TNF-α-mediated apoptosis." (PMID 18781150, 2008). "Furthermore, given the high retinoids content of the peritoneal adipose tissue, it is also likely that RA-signaling impacts on Cxcl13 expression, homing of leukemia to the peritoneal cavity, and consequently FALC formation." (PMID 29725010, 2018). "miR-494-3p was mainly paired with immune genes (CD3G, CXCL13, CXCR5, KLRC4), some of which had been annotated as oncogenes in leukemia including IGF1 (DRG; pan-cancer), IKZF3 (driver; leukemia), NABP1 (oncogene; leukemia), and PDGFRA (oncogene; pan-cancer)." (PMID 32605588, 2020).
liver cancer (6 papers, 2015 to 2024). An epithelial or non-epithelial malignant neoplasm that arises from the liver. "Recent studies have reported prominent overexpression of CXCL13 in liver cancer tissues and the serum of HCC patients." (PMID 39611128, 2024). "In contrast, proliferative pre-exhausted CD8+MKI67+CXCL13+) and regular pre-exhausted T cells (CD8+CXCL13+) were enriched in liver cancers with high clonality." (PMID 36980203, 2023). "In this study, we confirmed the high level CXCL13 was existed in both tissue and serum of advanced liver cancer patients." (PMID 26161394, 2015). "In this study, our observation of elevated rate of high level CXCL13 in advanced liver cancer patients indicated a very close relation between CXCL13 and liver cancer." (PMID 26161394, 2015). "The effect of CXCL13 on promoting liver cancer is related to the activation of Wnt/β-catenin pathway and the facilitation of IL-12, IL-17 and IgG4." (PMID 26161394, 2015). "We observed a considerable overexpression of CXCL13 in both liver cancer tissues and serum, and its level was positively correlated with serum ALT and AST." (PMID 26161394, 2015). "Furthermore, we also analyzed the relationship between CXCL13 and clinical features of liver cancer patients." (PMID 26161394, 2015). "Thus the serum CXCL13 level was associated with the progression of HCC, and it might be a potential biomarker for liver cancer progression." (PMID 26161394, 2015). "It was noted that memory CD4 T cells (CD4+CD69+) were enriched in liver cancers with low clonality, while proliferative pre-exhausted CD4 T cells (CD4+MKI67+CXCL13+) were enriched liver cancers with high clonality and a major source of cytokines and chemokines." (PMID 36980203, 2023). "Cytotoxic CD8 T cells (CD8+GNLY+) were found to be a major source of cytokines and chemokines secretion in liver cancers with low clonality, while proliferative pre-exhaustion T cells (CD8+MKI67+CXCL13+) were the main source in liver cancers with high clonality." (PMID 36980203, 2023).
lymphoproliferative disorders (6 papers, 2019 to 2022). "CXCL13 acts as a B-cell chemoattractant in lymphoid neogenesis and is widely involved in the autoimmune pathogenesis and lymphoproliferative disorders." (PMID 35570844, 2022).
meningoencephalitis (6 papers, 2015 to 2025). Inflammation of the meninges and brain, generally secondary to an infectious cause. "This sub-analysis accordingly underlined a broader function of CXCL13/CXCR5 signaling in meningoencephalitis and corroborated earlier observations linking persistent CXCL13 elevations with severe disease courses in bacterial and viral CNS infections." (PMID 34446066, 2021). "In the present state of knowledge, this intermediate stage (between the hemolymphatic stage and the meningoencephalitis stage) can be defined only on the basis of our biomarker levels CXCL-13 and neopterin." (PMID 31886231, 2019). "Moreover, following the resolution of symptoms, CXCL13 levels decreased only in patients with meningoencephalitis." (PMID 34638953, 2021). "Summing up, we found a clear link between intrathecal CXCL13 elevations and CXCR5+CD4 T cells in particular in meningoencephalitis patients and CXCR5+CD4 T cell correlating with B cell frequencies in neuroimmunological disorders." (PMID 34446066, 2021).
oral cancer (6 papers, 2011 to 2025). "A three-gene expression signature including IL-7, LTB, and CXCL13 was associated with LN neogenesis in human oral cancer, where higher grades of TLS were associated with improved disease-free survival (DFS) and overall survival (OS)." (PMID 40475770, 2025). "Inversely, oral cancer-associated TLSs with upregulation of CXCL13 are linked to the extended survival of oral cancer patients, indicating the roles of TLSs as a prognostic marker and immune treatment for oral cancer." (PMID 34947813, 2021). "CXCL2 and CXCL13 are associated with bone destruction in oral cancer and promote tumor invasion." (PMID 33330624, 2020).
relapsing-remitting MS (6 papers, 2017 to 2023). "CXCL13 is highly upregulated in active MS lesions and in the cerebrospinal fluid (CSF) of relapsing-remitting MS (RRMS) patients, with peaks of expression during relapses." (PMID 36232832, 2022). "In relapsing-remitting MS patients, immunohistochemical and quantitative PCR analyses have detected increased levels of CXCL13 in perivascular spaces and the extracellular matrix in early and highly active MS lesions characterized by high numbers of CD68+ macrophages." (PMID 38203597, 2023). "Notably, in patients with relapsing-remitting MS (RRMS), CSF CXCL13 levels are associated with increased relapse rate and disease severity measured by the expanded disability status scale (EDSS)." (PMID 35309354, 2022). "One of them revealed overexpression of the CXCL13 gene in active demyelinating lesions areas, the presence of the CXCL13 protein both in perivascular and parenchymal inflammatory infiltrates and elevated levels of CXCL13 in the cerebrospinal fluid (CSF) of patients with relapsing-remitting MS." (PMID 32110891, 2020).
secondary progressive MS (6 papers, 2011 to 2023). "ELSs with a network of CXCL13+ cells, have been detected in the meninges of approximately 40% of secondary progressive MS (SPMS) patients, and are associated with more severe disease course and cortical lesions." (PMID 35309354, 2022). "In one of the original articles describing ELFs in patients with secondary progressive MS (SPMS), the investigators found “a network of follicular dendritic cells producing CXCL13”." (PMID 36140203, 2022).
T cell lymphoma (6 papers, 2018 to 2025). "T-cell lymphomas such as AITL and PTCL release cytokines like IL-10 and CXCL13, fostering a suppressive and angiogenic environment that drives aggressive behavior." (PMID 40801653, 2025). "The presence of aggregates or sheets of atypical T-cells with clear cytoplasm, expressing CD10 and CXCL13, must alert the pathologist of a potential diagnosis of T-cell lymphoma rather than cHL." (PMID 36428786, 2022).
viral meningitis (6 papers, 2010 to 2022). Inflammation of the membranes surrounding the brain and spinal cord due to a viral infection. "CSF concentrations of CXCL13 were significantly elevated in patients with CIS-RRMS, Lues, LNB, and bacterial and viral meningitis, CXCL11 CSF concentrations in all patients groups except CIS/RRMS and SPMS." (PMID 31727097, 2019). "Elevated CSF CXCL13 levels were also detected in three controls with viral meningitis (enterovirus n = 1, varicella-zoster virus n = 2) while other CNS affections such as idiopathic facial palsy did not lead to CXCL13 elevation." (PMID 28859668, 2017). "Interestingly, among children with other specific diagnoses and pleocytosis in CSF (viral meningitis n = 4 and post infectious encephalitis n = 2), no patient had elevated CXCL13 in CSF." (PMID 30083887, 2018). "Such a sporadic elevation of CXCL13 in the CSF of patients with viral meningitis (VZV, enterovirus, TBEV, herpes simplex virus) had already been observed in previous studies and probably reflects a rare transient induction of CXCL13 in the virally infected CNS." (PMID 28859668, 2017).
atopic dermatitis (5 papers, 2011 to 2026). "Atopic dermatitis increased the expression of CXCL13 in the sera of BALB/c mice in a SOCS1-dependent manner." (PMID 30459600, 2018). "Atopic dermatitis increased the number of degranulated MCs in a CXCL13-dependent manner." (PMID 30459600, 2018). "Atopic dermatitis increased the expression levels of CD163, SOCS1, MIP-2, COX-2, HDAC3, COX-2, and MCP1 but decreased the expression of iNOS in a CXCL13-dependent manner." (PMID 30459600, 2018).
cervical cancer (5 papers, 2021 to 2025). A primary or metastatic malignant neoplasm involving the cervix. "For example, a CpG dinucleotide on the HIF-1a transcription factor motifs in the promoter element of CXCL13 in cervical cancer cells was consistently methylated and thus associated with HIF-1a." (PMID 34833360, 2021). "In a xenograft model with CXCL13 overexpression and S110 treatment, tumor growth and liver metastasis were suppressed, whereas its low expression increased the risk of death in cervical cancer patients." (PMID 34833360, 2021). "The downregulation of CXCL13 has been linked to hypermethylation of certain genes in cervical cancer cell lines and primary tumor biopsies." (PMID 34833360, 2021). "Our findings extend these observations to cervical cancer, suggesting that CXCL13+ T cells contribute to a robust immune microenvironment that enhances CCRT efficacy and suppresses recurrence." (PMID 40464813, 2025). "Although there are few studies in cervical cancer, one study suggests that CXCL13 inhibits cervical cancer metastasis." (PMID 38459390, 2024). "Recently it was shown that hypermethylation of single CpG dinucleotides at the promoter of CXCL13 gene stimulates cell migration in cervical cancer." (PMID 34833360, 2021). "The hypermethylation of a single CpG dinucleotide in the promoter region of the CXCL13 gene promoted the migration of cervical cancer cells." (PMID 34321012, 2021).
colorectal tumors (5 papers, 2018 to 2024). "Specifically, cytokines that were previously shown to correlate with the cytolytic index (C1QA, C1QB, C1QC, CXCL9, CXCL10, CXCL11 and CXCL13), were upregulated in CYT-high colorectal tumors." (PMID 31429779, 2019).
cryptococcosis (5 papers, 2013 to 2023). An acute or chronic, localized or disseminated infection by Cryptococcus neoformans. "Cryptococcosis and neurosyphilis are among the few other infectious diseases in which CSF CXCL13 levels as high as those in LNB have been reported." (PMID 23294475, 2013).
diffuse large B-cell lymphoma (5 papers, 2010 to 2025). "The only protein that was found to be associated with diffuse large B-cell lymphoma was CXCL13: its plasma levels increase over time, and, thus, it can be used as a biomarker." (PMID 41008635, 2025). "At any rate, studies to find protein biomarkers have also been conducted: in 2009, a study confirmed the relationship between diffuse large B cell lymphoma (the most common aggressive type) and the chemokine CXCL13 expression." (PMID 41008635, 2025). "CXCL13 is significantly increased in diffuse large B-cell lymphoma resistance to chemotherapy and is involved in tumor progression." (PMID 34947813, 2021). "CXCL13 plays a key role in the microenvironment of diffuse large B-cell lymphoma (DLBCL)." (PMID 34947813, 2021).
endometrial cancer (5 papers, 2022 to 2025). Primary or metastatic malignant neoplasm involving the endometrium (mucous membrane that lines the endometrial cavity). "Moreover, the impact of CXCL13 on endometrial carcinoma is currently missing in the literature." (PMID 38459390, 2024).
glioblastoma (5 papers, 2020 to 2023). The most malignant astrocytic tumor (WHO grade IV). "Other tumors, such as glioblastoma, anaplastic oligodendroglioma, anaplastic astrocytoma, diffuse astrocytoma, ependymoma, and medulloblastoma, had a lower expression of CXCL13 protein (e‐l)." (PMID 32314548, 2020).
liver disease (5 papers, 2010 to 2025). "The role of chemokines in liver disease was the subject of a seminal review, and in the present study, CXCL13 was minimally (1.5-fold, p < 0.05) induced to possibly stimulate the homing and motility of B cells to sites of injury." (PMID 36674967, 2023). "Similar induction of CCL21, CXCL16, CXCL9 and CXCL13 in the liver in other models of hepatic disease suggests that common mechanisms regulate the recruitment of lymphocytes to the liver following inflammation." (PMID 20502518, 2010).